CALCOCO1 (calcium binding and coiled-coil domain 1)
Description:
Functions as a coactivator for aryl hydrocarbon and nuclear receptors (NR). Recruited to promoters through its contact with the N-terminal basic helix-loop-helix-Per-Arnt-Sim (PAS) domain of transcription factors or coactivators, such as NCOA2. During ER-activation acts synergistically in combination with other NCOA2-binding proteins, such as EP300, CREBBP and CARM1. Involved in the transcriptional activation of target genes in the Wnt/CTNNB1 pathway. Functions as a secondary coactivator in LEF1-mediated transcriptional activation via its interaction with CTNNB1. Coactivator function for nuclear receptors and LEF1/CTNNB1 involves differential utilization of two different activation regions (By similarity). In association with CCAR1 enhances GATA1- and MED1-mediated transcriptional activation from the gamma-globin promoter during erythroid differentiation of K562 erythroleukemia cells. Seems to enhance inorganic pyrophosphatase thus activating phosphogluomutase (PMG). Probably functions as a component of the calphoglin complex, which is involved in linking cellular metabolism (phosphate and glucose metabolism) with other core functions including protein synthesis and degradation, calcium signaling and cell growth.
Synonyms: KIAA1536; PP13275; calphoglin; Cocoa
Tractability: PROTAC: ubiquitination databases record sites on it; its protein half-life has been measured.
Gene: Protein-coding gene on chromosome 12 (53,708,517 to 53,727,745, reverse strand). Ensembl gene ENSG00000012822.
Subcellular location: Cytoplasm; Nucleus
Subcellular location (Human Protein Atlas): Cytosol
Gene Ontology:
Molecular function: beta-catenin binding; protein binding; RNA polymerase II cis-regulatory region sequence-specific DNA binding; sequence-specific DNA binding; transcription coactivator activity; transcription coregulator activity; chromatin binding
Biological process: positive regulation of DNA-templated transcription; positive regulation of gene expression; nuclear receptor-mediated steroid hormone signaling pathway; positive regulation of transcription by RNA polymerase II; signal transduction
Cellular component: cytosol; nucleus; chromatin; cytoplasm
Genetic constraint (gnomAD): Loss-of-function variants: 41 observed, 84.54 expected, observed/expected ratio (o/e) 0.48, 90% interval 0.38 to 0.63. The upper end of that interval is the gene's LOEUF score, 0.63, which puts it in group 2 of 6, group 1 being the genes least tolerant of losing a copy. Missense variants: 694 observed, 862.69 expected, observed/expected ratio (o/e) 0.8, 90% interval 0.75 to 0.86. Synonymous variants: 292 observed, 336.04 expected, observed/expected ratio (o/e) 0.87, 90% interval 0.79 to 0.96.
Homologues: Orthologues: chimpanzee CALCOCO1 (99% identical), macaque CALCOCO1 (98% identical), pig CALCOCO1 (93% identical), guinea pig CALCOCO1 (92% identical), dog CALCOCO1 (92% identical), rabbit CALCOCO1 (91% identical), mouse Calcoco1 (89% identical), rat Calcoco1 (89% identical), tropical clawed frog calcoco1 (37% identical), zebrafish calcoco1a (33% identical), zebrafish calcoco1b (26% identical). Paralogues in human: TAX1BP1 (28% identical), CALCOCO2 (18% identical).
Diseases named in the same sentence as CALCOCO1 in open-access papers:
CALCOCO1 is named in the same sentence as 15 diseases in open-access papers, as found by Europe PMC text mining. Sharing a sentence is not in itself a finding about the gene and the disease. The quoted sentences say what the papers report.
breast carcinoma (6 papers, 2009 to 2025). "According to earlier studies, the N-terminal R12H of CALCOCO1 is associated with colorectal cancer metastasis and breast cancer development." (PMID 38262996, 2024). "N-terminal R12H of CALCOCO1 was found to be one of the risk factors of breast cancer in previous studies." (PMID 34571977, 2021). "Consequently, CALCOCO1 mutation-induced ER-phagy deficiency may be associated with the development of breast cancer." (PMID 38262996, 2024). "Therefore, it seems likely that the impaired ER-phagy caused by CALCOCO1 mutation could contribute to the occurrence of breast cancer." (PMID 34571977, 2021). "These included β-catenin-mediated transcription-related CALCOCO1, breast cancer poor-prognosis marker SBEM, and SMARCC2, a member of SWI/SNF chromatin-remodeling complex interacting with BRCA1." (PMID 21542898, 2011). "In this study, we observed nominally significant associations with only 2 variants and breast cancer risk (His52Arg in NCOR2 and Arg12His in CALCOCO1), which is in line with expectation based on the number of tests that were performed (2 of 40 = 5%)." (PMID 19183483, 2009). "CALCOCO1 expression has also been found to be altered in CRC and breast cancer, and this may also be linked to an alteration in the WNT/β-catenin signaling pathways but through an ill-described function of CALCOCO1 in transcription." (PMID 35188422, 2022). "Similarly, XBP1 has been shown to upregulate methyltransferase-like 3 (METTL3) and METTL4 to enrich m6a methylation and thus promote the mRNA stability of Calcium Binding And Coiled-Coil Domain 1 (CALCOCO1) and p62 (known ER-phagy regulators) in breast cancers." (PMID 41301006, 2025).
colorectal cancer (3 papers, 2020 to 2022). A primary or metastatic malignant neoplasm that affects the colon or rectum. "Studies have shown that the mRNA and protein levels of CALCOCO1 are depressed in colorectal cancer; it is likely that CALCOCO1 works as a tumor inhibitor, related to cancer cell metastasis." (PMID 35327508, 2022). "CALCOCO1 levels are depressed in colorectal cancer; it may also function as a tumor suppressor and is related to cancer cell motility and metastasis." (PMID 36009461, 2022). "For instance, a previous study demonstrated that lnc00052 could regulate CALCOCO1 expression via regulating miR-574-5p in colorectal cancer (CRC)." (PMID 32423385, 2020).
lung carcinoma (2 papers, 2012 to 2023). "CALCOCO1 is an autophagy-associated protein and a transcriptional coactivator with TCF/LET and beta-catenin, but its role in lung cancer is unclear." (PMID 37821974, 2023).
schizophrenia (2 papers, 2021 to 2023). A major psychotic disorder characterized by abnormalities in the perception or expression of reality. "ER vacuolization is associated with multiple neurological disorders, especially single-nucleotide polymorphism of the receptor CALCOCO1, which increases the risk of tardive dyskinesia in schizophrenia." (PMID 37376599, 2023). "Post-hoc analysis revealed that SNPs harbored in TNFRSF1B and CALCOCO1 independently conferred three-fold increase in TD risk, beyond clinical risk factors like Age of onset and Duration of illness to schizophrenia." (PMID 34103471, 2021).
glioma (1 paper, 2024). A benign or malignant brain and spinal cord tumor that arises from glial cells (astrocytes, oligodendrocytes, ependymal cells). "HOTAIR can also repress two crucial target genes, Calcium Binding And Coiled-Coil Domain 1 (CALCOCO1) and zinc finger CCCH-type containing 10 (ZC3H10), directly involved in the modulation of sensitivity to TMZ in U251 glioma cells." (PMID 38887279, 2024).
lymph node metastasis (1 paper, 2022). "The lower feature value of CALCOCO1|22108|RI, the higher probability of lymph node metastasis, indicating protecting role of CALCOCO1|22108|RI in LNM." (PMID 36713568, 2022).
tumor (5 papers, 2012 to 2022). "The most significant target genes were putative tumor oncogenes/promoters (TK1, KIF2C, UBE2C, AURKB) and potential tumor suppressors (CALCOCO1, CIRBP, KLHDC1, CBX7)." (PMID 36358602, 2022).
cancer (4 papers, 2013 to 2025). A tumor composed of atypical neoplastic, often pleomorphic cells that invade other tissues. "In the context of neurodegeneration, CALCOCO1 dysfunction may contribute to Golgi homeostasis disruption that leads to neurodegenerative diseases, cancers, etc.." (PMID 41153414, 2025). "The genes MACC1, PEG10, CALCOCO1, and MEF2C have been found to be implicated in cancer." (PMID 24086395, 2013).
CALCOCO1 also shares sentences with these, for which no sentence is quoted: acute lymphoblastic leukemia (1 paper); colon cancer (1); Huntington disease (1); metastatic disease (1); neurodegenerative disease (1); neurological disorders (1); panic disorder (1).